SPAST (spastin)
Description:
ATP-dependent microtubule severing protein that specifically recognizes and cuts microtubules that are polyglutamylated. Preferentially recognizes and acts on microtubules decorated with short polyglutamate tails: severing activity increases as the number of glutamates per tubulin rises from one to eight, but decreases beyond this glutamylation threshold. Severing activity is not dependent on tubulin acetylation or detyrosination. Microtubule severing promotes reorganization of cellular microtubule arrays and the release of microtubules from the centrosome following nucleation. It is critical for the biogenesis and maintenance of complex microtubule arrays in axons, spindles and cilia. SPAST is involved in abscission step of cytokinesis and nuclear envelope reassembly during anaphase in cooperation with the ESCRT-III complex. Recruited at the midbody, probably by IST1, and participates in membrane fission during abscission together with the ESCRT-III complex. Recruited to the nuclear membrane by IST1 and mediates microtubule severing, promoting nuclear envelope sealing and mitotic spindle disassembly during late anaphase. Required for membrane traffic from the endoplasmic reticulum (ER) to the Golgi and endosome recycling. Recruited by IST1 to endosomes and regulates early endosomal tubulation and recycling by mediating microtubule severing. Probably plays a role in axon growth and the formation of axonal branches. [Isoform 1]: Involved in lipid metabolism by regulating the size and distribution of lipid droplets.
Synonyms: ADPSP; FSP2; KIAA1083; SPG4
Tractability: Small molecule: a structure with a bound ligand is known. Antibody: UniProt places it where antibodies can reach, with high confidence. PROTAC: ubiquitination databases record sites on it; its protein half-life has been measured.
Target class: Isomerase; Enzyme
Chemical probes: Spastazolin (high quality)
Gene: Protein-coding gene on chromosome 2 (32,063,530 to 32,157,637, forward strand). Ensembl gene ENSG00000021574.
Subcellular location: Membrane; Endoplasmic reticulum; Midbody; Cytoplasm, cytoskeleton, microtubule organizing center, centrosome; Cytoplasm, cytoskeleton; Cytoplasm, perinuclear region; Nucleus; Cytoplasm, cytoskeleton, spindle; Cytoplasm; Cell projection, axon; Endoplasmic reticulum membrane (Isoform 1); Nucleus membrane; Lipid droplet; Endosome; Cytoplasm (Isoform 3)
Subcellular location (Human Protein Atlas): Nucleoplasm; Cytosol
Pathways (Reactome):
Cell Cycle: Sealing of the nuclear envelope (NE) by ESCRT-III
Gene Ontology:
Molecular function: alpha-tubulin binding; beta-tubulin binding; microtubule binding; microtubule severing ATPase activity; protein binding; ATP hydrolysis activity; protein-containing complex binding; ATP binding
Biological process: cytokinetic process; endoplasmic reticulum to Golgi vesicle-mediated transport; exit from mitosis; membrane fission; microtubule bundle formation; microtubule severing; mitotic cytokinesis; mitotic spindle disassembly; nuclear membrane reassembly; positive regulation of cytokinesis; protein hexamerization; protein homooligomerization; anterograde axonal transport; axonal transport of mitochondrion; central nervous system neuron axonogenesis; cytoskeleton-dependent cytokinesis; mitotic nuclear membrane reassembly; axonogenesis; positive regulation of microtubule depolymerization
Cellular component: axon; centrosome; cytoplasm; cytoplasmic vesicle; cytosol; endoplasmic reticulum; endoplasmic reticulum membrane; endosome; extracellular exosome; lipid droplet; membrane; microtubule cytoskeleton; midbody; nuclear membrane; nucleoplasm; nucleus; perinuclear region of cytoplasm; spindle pole; spindle; axon cytoplasm; cytoskeleton; microtubule
Genetic constraint (gnomAD): Loss-of-function variants: 14 observed, 31.71 expected, observed/expected ratio (o/e) 0.44, 90% interval 0.29 to 0.69. The upper end of that interval is the gene's LOEUF score, 0.69, which puts it in group 2 of 6, group 1 being the genes least tolerant of losing a copy. Missense variants: 528 observed, 542.7 expected, observed/expected ratio (o/e) 0.97, 90% interval 0.9 to 1.04. Synonymous variants: 245 observed, 209.58 expected, observed/expected ratio (o/e) 1.17, 90% interval 1.05 to 1.3.
Homologues: Orthologues: chimpanzee SPAST (100% identical), macaque SPAST (99% identical), dog SPAST (96% identical), guinea pig SPAST (96% identical), pig SPAST (94% identical), rat Spast (93% identical), mouse Spast (92% identical), rabbit SPAST (75% identical), tropical clawed frog spast (73% identical), zebrafish spast (61% identical), Drosophila melanogaster spas (49% identical), Caenorhabditis elegans spas-1 (33% identical). Paralogues in human: FIGNL1 (33% identical), VPS4B (26% identical), FIGN (25% identical), KATNAL1 (25% identical), VPS4A (25% identical), KATNA1 (25% identical), KATNAL2 (24% identical), FIGNL2 (23% identical), ATAD1 (20% identical).
Diseases named in the same sentence as SPAST in open-access papers:
SPAST is named in the same sentence as 119 diseases in open-access papers, as found by Europe PMC text mining. Sharing a sentence is not in itself a finding about the gene and the disease. The quoted sentences say what the papers report.
hereditary spastic paraplegia (104 papers, 2008 to 2026). Hereditary spastic paraplegias (HSP) comprise a genetically and clinically heterogeneous group of neurodegenerative disorders characterized by progressive spasticity and hyperreflexia of the lower limbs. "In this report, we describe a novel frameshift variant in the SPAST gene identified in two siblings affected by hereditary spastic paraplegia from a Turkish–Bulgarian family." (PMID 41149788, 2025). "Our work thus provides mechanistic insight into the control of microtubule-driven neuronal development and homeostasis and opens new avenues for developing therapeutic strategies in spastin-associated hereditary spastic paraplegia." (PMID 39613968, 2025). "Mutations of SPAST, which encodes SPASTIN, a microtubule-severing protein, are considered the most common cause of hereditary spastic paraparesis (HSP)." (PMID 35418834, 2022). "Mutations of the spastin (SPG4 and SPAST) gene are the main causes in patients suffering from hereditary spastic paraplegia." (PMID 35858336, 2022). "Spastin significantly influences microtubule regulation in neurons and is implicated in the pathogenesis of hereditary spastic paraplegia (HSP)." (PMID 35869491, 2022). "Mutations of the SPAST gene that encodes the microtubule-severing enzyme called spastin are the chief cause of Hereditary Spastic Paraplegia." (PMID 34439700, 2021). "Other microtubule-severing enzymes are also important for neural cell homeostasis and function, such as Spastin, whose mutations lead to defects in axonal transport and degeneration, and diseases like hereditary spastic paraplegia (HSP)." (PMID 34414183, 2021). "Disrupting this interaction led to the missorting of lysosomal enzymes and lysosomal defects, which is likely to be the underlying reason why spastin mutations cause hereditary spastic paraplegia." (PMID 34571990, 2021). "When mutated, Spastin impairs this synchronization between organelle dynamics, and affects other proteins involved in hereditary spastic paraplegia, notably REEP1 and Seipin." (PMID 32315314, 2020). "Hereditary spastic paraplegia is a central motor axonopathy predominantly caused by mutations in SPAST, encoding the microtubule-severing protein spastin." (PMID 32321733, 2020). "Mutations in the gene encoding the microtubule severing ATPase spastin are the most frequent cause of hereditary spastic paraplegia, a genetic condition characterised by length-dependent axonal degeneration." (PMID 31587092, 2020). "Hereditary Spastic Paraplegia (HSP) is a neurodegenerative disease most commonly caused by autosomal dominant mutations in the SPG4 gene encoding the microtubule-severing protein spastin." (PMID 33106322, 2020). "Here, we report a novel mutation in SPAST gene associated with hereditary spastic paraplegia in a Chinese family, further enriching the hereditary spastic paraplegia spectrum." (PMID 32493220, 2020). "Mutations in the SPAST gene have been linked to hereditary spastic paraplegia (HSP), a condition characterized by degeneration of nerve fibers in the corticospinal tracts." (PMID 33122304, 2020). "Microtubule-dependent peroxisome movement is found to be impaired in cells with spastin gene (SPAST) mutations from patients with Hereditary Spastic Paraplegia." (PMID 29510535, 2018). "Mutations of the SPG4 (SPAST) gene encoding for spastin protein are the main causes of hereditary spastic paraplegia." (PMID 30213879, 2018). "We found that patients with hereditary spastic paraplegia caused by genomic deletions of SPAST that extended into DPY30 had a significantly younger age at onset." (PMID 29481671, 2018). "The disruption of Spastin-mediated vesicular transport has been discussed as a cause of hereditary spastic paraplegias, with symptoms such as the progressive stiffness of lower limbs due to nerve dysfunction, cognitive impairments and deafness." (PMID 27188386, 2017).
hereditary spastic paraplegia (continued). "The PMP22 duplication is the most common cause of CMT; spinal muscle atrophy is mostly caused by deletions in the SMN1 gene and deletions of SPAST have been identified in hereditary spastic paraplegia." (PMID 25648254, 2015). "Mutations of spastin causing Hereditary Spastic Paraplegia (HSP) often compromise the severing ability of spastin, which is considered a loss of function effect." (PMID 26691836, 2015). "The patients were all diagnosed with adult onset Hereditary Spastic Paraplegia by a neurologist (CS) and in each case a mutation in SPAST was identified: the mutations included single nucleotide substitutions, insertions and deletions." (PMID 24857849, 2014). "It is interesting to note that mutation of TBCE in mice results in a progressive motor neuropathy while mutations in spastin are the cause of the most common form of hereditary spastic paraplegia in humans, likely through disruption of axonal transport." (PMID 23840848, 2013). "Mutations in spastin are the most common cause for hereditary spastic paraplegia (HSP), a heterogeneous group of neurodegenerative disease affecting primarily the long axons of corticospinal tracts in the spinal cord." (PMID 22216323, 2011). "ZFYVE27 (Protrudin) was originally identified as an interacting partner of spastin, which is most frequently mutated in hereditary spastic paraplegia." (PMID 22216323, 2011). "Mutations in the gene encoding the microtubule (MT)-severing protein spastin are the most common cause of hereditary spastic paraplegia, a genetic condition in which axons of the corticospinal tracts degenerate." (PMID 19000169, 2009). "Spastin is a conserved microtubule-severing enzyme mutated in hereditary spastic paraplegia." (PMID 41633839, 2026). "SPAST mutations are the most common cause of hereditary spastic paraplegia." (PMID 36971361, 2023). "In the three hereditary spastic paraplegia families, of whom three index cases were misdiagnosed as other types of neurological diseases, a novel c.985dupA (p.Met329Asnfs*3) variant in SPAST was identified and was shown to cosegregate with the phenotype in the three families." (PMID 34927746, 2022). "Moreover, SPAST haploinsufficiency in human and animal models causes hereditary spastic paraplegia (HSP) with cerebellar ataxia via disrupting microtubule organization and axonal transport of cargoes (including mitochondria)." (PMID 34691693, 2021). "Spastin mutations represent the most common cause of hereditary spastic paraplegia." (PMID 32315314, 2020). "Mutations of the SPG4 (SPAST) gene are the main causes of hereditary spastic paraplegia." (PMID 30886064, 2019). "Mutations in SPG4-encoding spastin cause hereditary spastic paraplegia (HSP)." (PMID 30082270, 2018). "In contrast, in hereditary spastic paraplegia (HSP) caused by mutations of the gene encoding spastin (spg4 alias SPAST), spastin function in terms of microtubule severing is decreased at least for the gene product of the mutated allele, resulting in overstable microtubules in disease model systems." (PMID 26691836, 2015). "In addition, mutations in the gene spastin, which encodes a MT severing protein, are the cause of the most common form of hereditary spastic paraplegia in humans." (PMID 23840848, 2013). "Spastin, an ATP-dependent microtubule-severing enzyme, is known to cause a human neurodegenerative disease, hereditary spastic paraplegia (HSP)." (PMID 40178516, 2025). "Mutations in the SPAST gene fulfill a crucial role in hereditary spastic paraplegia (HSP) due to being found in almost 40% of inherited HSP patients and approximately 20% of sporadic patients (single individuals with the disorder in the family)." (PMID 38732227, 2024). "Spastin is encoded by SPAST gene and its mutations was identified in patients with hereditary spastic paraplegia (HSP)." (PMID 38231910, 2024).
hereditary spastic paraplegia (continued). "Spastic paraplegia type 4 (SPG4), the predominant form of Autosomal Dominant Hereditary spastic paraplegia (AD-HSP), is characterized by variants in the SPAST gene." (PMID 39139823, 2024). "Loss-of-function mutations in spastin are the most common genetic cause of hereditary spastic paraplegias (HSP)." (PMID 36414997, 2022). "Spastic paraplegia type 4 (SPG4) is the most common type of hereditary spastic paraplegia (HSP) caused by mutations in the SPAST gene." (PMID 34950521, 2021). "Mutations of the SPAST gene (also called SPG4) account for the plurality of cases of autosomal dominant Hereditary Spastic Paraplegia (HSP), a heritable neurodegenerative disease involving progressive weakness and spasticity of lower limbs." (PMID 34439700, 2021). "Spastin mutations can cause hereditary spastic paraplegia (HSP); thus, defects in MCS‐mediated endosomal fission and downstream effects on lysosomal function were proposed to underlie axonal degeneration in HSP." (PMID 32129938, 2020). "Among them, spastin is encoded by the SPAST gene, which is mutated in the most common form of dominant hereditary spastic paraplegia (HSP), a progressive neurological disease characterized by the dying-back of the long corticospinal axons." (PMID 32321733, 2020). "Mutations of the SPAST gene are responsible for autosomal dominant cases of Hereditary Spastic Paraplegia (HSP); a group of neurodegenerative disorders affecting upper motor neurons." (PMID 32315314, 2020). "Mutations in the gene encoding the microtubule-severing protein spastin (spastic paraplegia 4 [SPG4]) cause hereditary spastic paraplegia (HSP), associated with neurodegeneration, spasticity, and motor impairment." (PMID 32866173, 2020). "For example, variants located in conserved splice sites of exon 12 of the SPAST gene lead to exon skipping and cause hereditary spastic paraplegia (HSP)." (PMID 31781178, 2019). "Autosomal dominant mutations in the gene encoding spastin (SPAST/SPG4) cause hereditary spastic paraplegia (HSP), a disease characterized by axonal degeneration in the central motor tracts." (PMID 28389476, 2017). "Mutations in SPAST, encoding spastin, are the most common cause of autosomal dominant hereditary spastic paraplegia (HSP)." (PMID 25875445, 2015). "Genetic mutations in the microtubule-severing enzyme Spastin, is most commonly associated with hereditary spastic paraplegia (HSP)." (PMID 26441521, 2015). "Mutations in SPAST/SPG4 encoding spastin represent the most common cause of autosomal dominant hereditary spastic paraplegias (AD-HSP) and also account for about 15% of sporadic cases." (PMID 24690193, 2014). "Mutations in AAA proteins like Spastin and Katanin are seen to be associated with Hereditary Spastic Paraplegia (HSP)." (PMID 27335666, 2012). "This research not only broadens the molecular understanding of complex hereditary spastic paraplegia (HSP) but also expands the known inheritance patterns of SPAST‐related disorders." (PMID 41000004, 2026). "Notably, hereditary spastic paraplegia (HSP) was a neuronal disease caused by gene mutations, such as those in the spastin gene (SPG4) and the kinesin family member 5 (KIF5) gene." (PMID 40303338, 2025). "Importantly, mutations in the SPG4 gene encoding the MT-severing enzyme spastin are responsible for the major form of autosomal dominant hereditary spastic paraplegia (HSP), a degenerative condition of the corticospinal tracts." (PMID 39613968, 2025). "Hereditary spastic paraplegia (HSP), a group of disorders caused by mutations in genes that regulate axonal transport (e.g., SPAST, ATL1), represents another area of genomic medicine." (PMID 40806492, 2025). "The method was shown to effectively distinguish SPG4/SPAST hereditary spastic paraplegia from both healthy donors and other subtypes of hereditary spastic paraplegia." (PMID 40076577, 2025).